PTPRZ1 (protein tyrosine phosphatase receptor type Z1)
Diseases named in the same sentence as PTPRZ1 in open-access papers (continued):
Sharing a sentence is not in itself a finding about the gene and the disease.
tumor (continued). "To evaluate the therapeutic potential of targeting the PTN–PTPRZ1 paracrine signalling in GBM treatment, we examined whether a specific anti-PTPRZ1 antibody could inhibit GSC-derived tumour growth." (PMID 28569747, 2017). "Furthermore, we found that PTPRZ1 actually has an important oncogenic role in tumor progression in the murine xenograft model." (PMID 23170925, 2012). "Because nitric oxide (NO) and NOS are ubiquitous in malignant tumors and known to exert pro-tumor effects, PTPRZ1 may regulate NO production in SCLC cells by changing the tyrosine phosphorylation status of CaM." (PMID 23170925, 2012). "A possible speculation is that the CA domain of PTPRZ1 could have an important function for tumor progression of SCLC and further studies will be required to address this issue." (PMID 23170925, 2012). "To determine whether overexpressed PTPRZ1 acts as a tumor suppressor or tumor promoter in human NETs, we used the severe combined immunodeficiency (SCID) murine xenograft model subcutaneously transplanted with human SCLC cells." (PMID 23170925, 2012). "Therefore, finding the key ligand and evaluate whether its binding to PTPRZ1 was essential for the tumor growth of LUSC could provide potential therapeutic target to treating the disease." (PMID 40899632, 2025). "PTPRZ1-based therapeutics could help overcome resistance to existing therapies and could be used in combination with chemotherapy or other targeted therapies, depending on the tumor type." (PMID 37175798, 2023). "In cervical carcinoma, PTPRZ1 expression was found significantly higher compared to the normal cervical epithelium, significantly higher in patients with smaller (≤2 cm) compared to those with larger (>2 cm) tumor sizes, and higher in squamous cell carcinoma than in adenocarcinoma." (PMID 37175798, 2023). "Likewise, downregulation of PTPRZ1 expression by siRNA in human GBM U251MG cells injected subcutaneously into nude mice or in an orthotopic intracerebral model has resulted in significantly decreased tumor growth." (PMID 37175798, 2023). "Functional studies demonstrate that PTPRZ1 is essential for LUSC‐tumorigenesis and tumor cells proliferation and migration in vitro and in vivo." (PMID 40899632, 2025). "CD163+ TAMs secrete pleiotrophin (PTN), which binds to its receptor on GSCs, protein tyrosine phosphatase receptor type Z1 (PTPRZ1), promoting self-renewal and sustainability that support tumor progression." (PMID 40361384, 2025). "Individual patient tumor organoids (IPTO) maintain tumor multicellular characteristics and are thereby suitable to study PTPRZ1-TCR-T-mediated alterations in a realistic multicellular-orchestrated microenvironment." (PMID 39893177, 2025). "Three of the TAAs (BCAN, PTPRZ1, BIRC5) are highly over-expressed in GBM tumours compared with healthy tissue (except testis)." (PMID 41051649, 2025). "Utilizing a published scRNA-seq dataset comprising 15 tumor samples and one nasopharynx, UMAP visualization revealed that SOX2, NTRK2, LRP6, and PTPRZ1 from our candidate list were predominantly expressed in epithelial and malignant patient cells." (PMID 40133476, 2025). "The tumor-suppressor von Hippel-Lindau (VHL) gene, which plays an important role in regulating the response to hypoxia, suppresses PTPRZ1 expression, potentially by suppressing HIF2 expression." (PMID 37175798, 2023). "Thus, PTPRZ1 could facilitate tumor development and therefore influence patients’ prognosis." (PMID 36874110, 2023). "The expression patterns of PTPN1 in human NB cells and NB tumor samples was investigated, in comparison with other PTPs, including PTPRH, PTPRZ1, and PTEN." (PMID 31837707, 2019).
tumor (continued). "NB tumor samples from 44 patients were analysed by immunohistochemistry using specific antibodies against PTPN1, PTPRH, PTPRZ1, and PTEN." (PMID 31837707, 2019). "Our previous study demonstrated that PTN and PTPRZ1 were highly expressed in recurrent TNBC tissue, which hinted at their tumour-promoting effects." (PMID 30497491, 2018). "Collectively, these data demonstrate that disrupting PTN–PTPRZ1 signalling by the anti-PTPRZ1 antibody impairs the supportive effect of TAMs, thus potently suppresses GSC tumour growth." (PMID 28569747, 2017). "In this study, we uncover that M2 TAMs preferentially secrete the cytokine PTN to impact GSCs through its receptor PTPRZ1 to promote GSC maintenance and tumour growth." (PMID 28569747, 2017). "Disrupting the PTN–PTPRZ1 signalling by shRNA or the antibody blockade against PTPRZ1 largely abrogates the tumour-supportive effects of PTN and suppresses GBM growth driven by the tumour-initiating GSCs." (PMID 28569747, 2017). "Among the most abundant sialoglycoproteins (median intensity >150,000) over-expressed in tumor cells, those with the largest Effect size (Effect size >5.0) include SLC1A3, PTPRZ1, GPR56 and CLU." (PMID 25360666, 2014). "Further experiments are needed to address the possibility of PTN mediating its effects via ALK in SCLC cells, the effects of PTN deletion on tumor growth, and the mechanism of PTN/PTPRZ1 autocrine regulation in NET cells." (PMID 23170925, 2012). "PTPRZ1 interacts with its ligand pleiotrophin (PTN), which is a secreted growth factor involved in angiogenesis and tumor growth." (PMID 23170925, 2012). "Here we demonstrate that PTPRZ1 specifically exists in human NET tissues and PTPRZ1 has an important oncogenic role in the tumor progression of SCLC in the murine xenograft model." (PMID 23170925, 2012). "PTPRZ1 is essential during neurodevelopment but not in adults; however, its expression re-emerges and is required for gliomagenesis and tumor progression." (PMID 39893177, 2025). "This analysis also showed that the maturation of the PTPRZ1–MET protein to the β chain in the tumor samples is similar to that of amplified MET, if not less efficient." (PMID 38254850, 2024). "As exemplified by PTPRZ1- and NLGN4X-specific T cells, their T cell receptors (TCR) were able to license transgenic T cells to exhibit cytotoxic activity towards target-expressing tumor cell lines, confirming natural processing within the tumor cells." (PMID 36303101, 2022). "Recently, emerging evidence has demonstrated that PTN/PTPRZ1 signalling might be involved in the carcinogenesis of several cancers; PTPRZ1 interacts with its ligand PTN to mediate tumour cell growth and metastasis." (PMID 30497491, 2018). "This contrasts sharply with the weak or absent correlation between tumor-infiltrating myeloid cells and expression of IL-34, PTPRZ1, and syndecan-1." (PMID 29796177, 2018). "To investigate PTPRZ1 expression pattern in GBMs, we co-immunostained PTRPZ1 and several GSC markers in frozen GBM specimens and found a preferential expression of PTPRZ1 in tumour cells expressing GSC markers SOX2, OLIG2 and CD133." (PMID 28569747, 2017). "To address whether the pro-tumorigenic effect of TAMs is exerted through PTPRZ1 expressed on GSCs, we determined the effect of PTN-expressing MLCs on the growth of PTPRZ1+ and PTPRZ1− tumours." (PMID 28569747, 2017). "Reduction of tumor growth as well as absence of growth effects have been reported for PTPRZ1 knock-down experiments." (PMID 25238264, 2014). "We hypothesized that PTPRZ1 functions to regulate tyrosine phosphorylation in SCLC cells and has an important role for SCLC tumor progression." (PMID 23170925, 2012). "Moreover, additional irradiation of tumor cells in vitro resulted in increased lysis of target cells likely due to enhanced activation of PTPRZ1-TCR-CD4+-T but not PTPRZ1-TCR-CD8+-T." (PMID 39893177, 2025).
tumor (continued). "In Ptprz1−/− mice, the number of mature B-cells is decreased, raising the hypothesis that this might be a mechanism through which PTPRZ1 affects cancer development depending on the inherent immunogenicity of each tumor." (PMID 37175798, 2023). "Identification of the PTPRZ1 downstream signaling pathways in the presence or absence of its ligands should help explain these opposing effects, that could be due to the diverse tumor microenvironments." (PMID 37175798, 2023). "To confirm that the antitumour effect of anti-PTPRZ1 antibody is exerted through blocking PTN–PTPRZ1 axis between GSC and TAMs, we constructed GBM xenografts co-implanted with GSCs (T4121) and MLCs, and administrated the tumour-bearing mice with anti-PTPRZ1 antibody." (PMID 28569747, 2017).
cancer (37 papers, 2010 to 2025). A tumor composed of atypical neoplastic, often pleomorphic cells that invade other tissues. "Analyses of intratumoral heterogeneity revealed that the expression levels of PTPRZ1 transcripts are markedly varied among individual cells and that the strong expression of these transcripts is closely associated with cancer stemness." (PMID 28717188, 2017). "Interestingly, analyses of intratumoral heterogeneity revealed that the level of PTPRZ1 overexpression is strongly associated with cancer stemness, signified by the definition of PTPRZ1 transcripts as a stemness classifier gene." (PMID 36303101, 2022). "In conclusion, hypoxia or chemical hypoxia regulates PTN and PTPRZ1 expression to restrict its stimulatory effects on endothelial and cancer cells." (PMID 40361445, 2025). "Further analysis revealed that MDK and NCL/PTPRZ1/LRP1 were highly expressed in cancer cells and astrocytes/cancer cells/macrophages in the MDK signaling pathway, respectively." (PMID 40527884, 2025). "The results suggested that multiple SOE co‐regulated the transcription of PTPRZ1, which ensured its robust expression in cancer cells." (PMID 40899632, 2025). "Single‐cell epigenomic profiling reveals these SOEs to be exclusively active in a cancer cell‐like cluster, pinpointing PTPRZ1, a receptor tyrosine phosphatase, as a top SOE‐driven candidate." (PMID 40899632, 2025). "PTPRZ1 activators, such as rebamipide, have been used to activate PTPRZ1 in PTPRZ1–downregulated cancer cells." (PMID 39518121, 2024). "The biological function of PTPRZ1 has been demonstrated in various cancers, such as small cell lung cancer, cervical carcinoma, oral squamous cell carcinoma, and gastric cancer." (PMID 39518121, 2024). "A liver-binding glycoprotein called polytrophin (PTN) is expressed by the CD11b+ CD163+ M2 TAMs, stimulating the growth and proliferation of cancer cells by binding to the protein PTPRZ1 (protein tyrosine phosphatase, receptor type Z1) on GBM cells." (PMID 37692522, 2024). "Third, a previous study showed that integrin α6β4 associated with cancer stem cells and negatively correlated with TNBC relapse-free survival in which PTPRZ1 shares the same features." (PMID 39518121, 2024). "According to recent studies, PTPRZ1 plays roles in cell proliferation, cell adhesion, migration, cancer stem cells, and treatment resistance through its interaction with various molecules." (PMID 38553684, 2024). "NFκΒ has a major role in the regulation of inflammation and cancer progression, and the validity of PTPRZ1 as a target to inhibit NFκΒ signaling in cancer deserves further investigation." (PMID 37175798, 2023). "In this review, we present evidence on the role of PTPRZ1 in angiogenesis and cancer and discuss the phenomenal differences among the different types of cancer, depending on the regulation of its tyrosine phosphatase activity or ligand binding." (PMID 37175798, 2023). "In conclusion, there is an increasing interest in PTPRZ1′s involvement in angiogenesis and cancer and its potential importance in the regulation of processes that drive carcinogenesis and/or cancer growth and invasion." (PMID 37175798, 2023). "Being considered a canonical cancer stem cell marker, PTPRZ1 has also been included in an integrative analysis of the heterogeneity present in GBM cancer stem cell populations by using a combination of flow cytometry and bulk and single-cell RNA-sequencing." (PMID 37175798, 2023). "More recently, α4β1, α6β1, and ανβ3 integrins were found to directly interact with PTPRZ1 in normal and cancer cells." (PMID 37175798, 2023). "In cancer, PTPRZ1 expression is upregulated or downregulated, as discussed later in this review, but how this is moderated in each case has not been elucidated." (PMID 37175798, 2023). "PTPRZ1 has different functions in the occurrence, development, and metastasis of cancer, which further affects cancer treatment and prognosis." (PMID 35251170, 2022).
cancer (continued). "Upregulation of several of these genes, for instance, PTPRZ1, WNT5A, S100A4, or ANXA1/2, has been linked to cancer invasion and aggressiveness in some solid tumors, including GBM25–30." (PMID 34112916, 2021). "We compared the expression of PTN and PTPRZ1 between normal breast and cancer tissues as well as before and after chemotherapy in cancer tissue using the microarray analysis data from the GEPIA database and GEO database." (PMID 30497491, 2018). "To assess mRNA expression of PTPRZ1 comprehensively in human cancers, we screened 20 cell lines from a variety of pathological phenotypes established from different organs by RT-PCR." (PMID 23170925, 2012). "PTPRZ1 may also prove to be a valuable biomarker for the choice of the best therapeutic protocol or to be used for selective targeting of cancer cells that overexpress it." (PMID 37175798, 2023). "In view of the up- and downregulation of PTPRZ1 in different cancers, the pharmacological inhibition or activation of PTPRZ1 may be a promising strategy for tumors treatment." (PMID 35251170, 2022). "PTPRZ1, p120, and β-catenin were abnormally expressed in cancer tissues." (PMID 35251170, 2022). "With regard to cancer, PTPRZ1 expression was dramatically induced by genetic amplification caused by chronic oxidative stress and hypoxic stress through HIF-2 alpha and several previous studies suggested that PTPRZ1 regulates cancer cell growth and cell migration." (PMID 23170925, 2012). "This study supports the idea that a new signaling pathway involving PTPRZ1 could be a feasible target for treatment of cancers." (PMID 23170925, 2012). "PTPRZ1 is linked to cancer relapse, but its role in TNBC is not well understood." (PMID 39518121, 2024). "PTPRZ1 is activated by MDK, fueling cancer via the PI3K pathway, and blocking PTPRZ1 stopped cancer cell growth and spread, revealing PTPRZ1‐MDK as a new treatment target for LUSC." (PMID 40899632, 2025). "PTPRZ1 overexpression on its own would be expected to abrogate AKT/mTOR signaling and cancer progression." (PMID 36966348, 2023). "PTPRZ1 plays a role in cell proliferation, adhesion and migration, EMT, cancer stem cells, and treatment resistance by interacting or binding with several molecules." (PMID 35251170, 2022). "First, we compared IL-34,CSF-1, CSF-1R, PTPRZ1, and SDC1 gene expression between human MCF7, SK-BR-3 and MDA-MB-231 cancer cells in comparison to human THP-1 macrophages." (PMID 29796177, 2018). "PTPRZ1 expression is also increased in other cancer types, but there are no data on the potential functional significance of this finding." (PMID 37175798, 2023). "The role of GPM6A or PTPRZ1 in the radioresistance of GB or other cancer types has never been reported." (PMID 35883571, 2022). "According to the TCGA data, PTPRZ1 may be related to OS and DFS in various cancers, which suggests PTPRZ1 is involved in survival signals." (PMID 35251170, 2022). "Whether and how this processing affects the implication of PTPRZ1 in cancer growth and metastasis and/or angiogenesis has never been addressed." (PMID 37175798, 2023).
adenocarcinoma (2 papers, 2012 to 2023). A common cancer characterized by the presence of malignant glandular cells. "In a recent bioinformatic analysis, PTPRZ1 mRNA levels were significantly decreased in both colon and rectum adenocarcinomas, and this decrease may be associated with overall and/or disease-free survival." (PMID 37175798, 2023).
infection (2 papers, 2024 to 2025). The state of being infected such as from the introduction of a foreign agent such as serum, vaccine, antigenic substance or organism. "For the cTEC: DP evaluation, the Ptn (pleiotrophin)-Ptprz1 interaction is observed in mock but not MRV infection." (PMID 38895117, 2024).
neurological diseases (1 paper, 2024). "Data showed that transgenic mice with Ptprz1 exhibit symptoms of neurological disorders, including memory decline, indicating that Ptprz1 may be a potential factor in neurological diseases." (PMID 39635132, 2024).
PTPRZ1 also shares sentences with these, for which no sentence is quoted: oligodendroglioma (3 papers); diabetes (2); heart failure (2); Lung Squamous Cell Carcinoma (2); malignant glioma (2); Alzheimer disease (1); anaplastic ependymoma (1); autism spectrum disorder (1); bone metastasis (1); cardiomyopathy (1); central nervous system disorder (1); cholangiocarcinoma (1); chronic kidney disease (1); demyelinating disease (1); depression (1); diffuse midline glioma (1); Ewing sarcoma (1); ganglioglioma (1); invasive breast carcinoma (1); keloid (1); left ventricular dilation (1); low grade glioma (1); lupus nephritis (1); Nervous (1); Obesity (1); ovarian serous cystadenocarcinoma (1); sarcoma (1); thyroid (1); type 2 diabetes mellitus (1).